DNMT3A (DNA methyltransferase 3 alpha)
Diseases named in the same sentence as DNMT3A in open-access papers (continued):
Sharing a sentence is not in itself a finding about the gene and the disease.
tumor (continued). "While the DNMT3A-regulated epigenetic changes in CAR-T cells induce exhaustion, removing DNMT3A from CAR-T cells improves the anti-tumor activities and avoids possible dysfunction in an IL-10-dependent manner." (PMID 37064017, 2023). "In this study, U2AF1, DNMT3A, SF3B1, and EZH2 in the secondary tumor group was higher than that in the tumor‐free group, while the mutation rate of ASXL1, TET2, and KMT2D was higher in the tumor‐free group." (PMID 36727544, 2023). "Not only did the DNMT3A-KO CAR-T cells retain proliferative capacity, but the cells also controlled a secondary tumor challenge, conserving memory potential and protecting against tumor relapse." (PMID 36853475, 2023). "The expression of four methylated transferases (DNMT1, DNMT2, DNMT3A and DNMT3B) in various tumor types was significantly correlated with the expression of PTPN2." (PMID 37884566, 2023). "Akin to what was observed in murine models of allo-HSCT, deletion of DNMT3A in CAR T-cells resulted in exhaustion-resistant cells with preservation of the cells’ proliferative capacity and ongoing anti-tumor response despite prolonged tumor exposure." (PMID 37325668, 2023). "DNMT3A is overexpressed in the early stages only, whereas DNMT1 and DNMT3L are also overexpressed in tumor relapses." (PMID 37894317, 2023). "At the same time, the expression levels of DNA methyltransferases (DNMT) (including DNMT1, DNMT3A and DNMT3B) in the normal and tumor samples from TCGA database were also determined." (PMID 37838802, 2023). "Inspiringly, we found miR-26a-5p regulated DNMT3A expression to remold DNA methylation pattern of SFRP1, therefore, modulated tumor growth and cancer stem cell-like properties via Wnt/β-catenin signaling pathway." (PMID 35860691, 2022). "In particular, it serves as a tumor suppressor in diverse malignancies by targeting critical oncogenes or anti-oncogenes, including EZH2, DNMT3a, MALAT-1, ZEB1, and USP47." (PMID 35205710, 2022). "The deletion of the de novo DNA methyltransferase 3 alpha (DNMT3A) in first- or second-generation CAR T cells universally preserved the cell proliferation and antitumor response during prolonged tumor exposure." (PMID 36275671, 2022). "Firstly, we began by comparing the expression of the DNMT1, DNMT3A, and DNMT3B methyltransferases in relation to MELK tumor expression, revealing that all three were up-regulated in the context of higher MELK expression." (PMID 35511171, 2022). "What’s more, the deletion of Dnmt3a in mouse promotes lung tumor progression, suggesting the critical roles of RMST in regulating tumor progression and development." (PMID 35356464, 2022). "The mRNA levels of DNA methyltransferases (including DNMT1, DNMT3A, and DNMT3B) were significantly higher in KIRC patients and correlated with tumor stage and histologic tumor grade than in normal." (PMID 36186442, 2022). "An analysis of the mean z-score in each data set revealed that DNMT3A, DNMT3B, and HDAC1/2/3 tended to have positively shifted z-scores indicating an increase in mean gene expression in the tumor populations." (PMID 36050516, 2022). "Recently, we demonstrated the overexpression of both DNA methyltransferase 3A (DNMT3A) and 3B (DNMT3B) in RMS tumour biopsies and cell lines compared to normal skeletal muscle." (PMID 34831178, 2021). "Intriguingly, studies on tumor growth have revealed the great potential of E2 in the induction of changes related to DNA methylation involving DNA methyltransferases (DNMT1, DNMT3A, and DNMT3B)." (PMID 33915762, 2021).
tumor (continued). "Other examples from this study include well-described tumor-promoting genes such as SRSF2, DNMT3A, ATM, BRCA1 and PKM, for which Tax- and HBZ-alternative splicing events are now associated with ATLL for the first time." (PMID 34543356, 2021). "Studies on tumor growth have demonstrated the great potential of E2 in the induction of changes involving DNMT1, DNMT3A, and DNMT3B related to DNA methylation." (PMID 33915762, 2021). "Our group also reported DNMT3A and DNMT3B overexpression in RMS tumour primary biopsies and cell lines compared to normal skeletal muscle, so revealing the oncogenic role of DNMT3B in ERMS cell lines." (PMID 34831178, 2021). "Increased expression of DNMT1, DNMT3A and DNMT3B has been detected in PDAC, which suggests direct involvement in the epigenetic regulation of tumor progression." (PMID 34198989, 2021). "Recently, we demonstrated the overexpression of DNMT1, DNMT3A, and DNMT3B in RMS tumour biopsies compared to normal skeletal muscle and the oncogenic role, which is played by DNMT3B in RMS." (PMID 34831178, 2021). "miR-29 is considered a tumor suppressor miRNA given its ability to repress genes involved in proliferation and cell survival, such as AKT3, DNMT3A/B, MCL1, and CDK6, and its frequent downregulation in cancer, including leukemia, ovarian, or breast." (PMID 33808771, 2021). "Decitabine is known to degrade DNMT1, DNMT3A, and DNMT3B proteins in tumor tissue by inducing lysosomal degradation of DNMTs." (PMID 32714333, 2020). "Although the DNMT3a level in tumor tissues was higher than that of the normal tissues, there was no statistical significance between the expression levels of OCT4 and DNMT3a in tumors." (PMID 31771617, 2019). "Of the 3 DNMTs both DNMT3A and DNMT3B increase their transcript level in tumor compared to matched normal samples of this cohort, as calculated from the RNA-seq data." (PMID 29394925, 2018). "In AML, microRNA-29b targets DNMT3A and DNMT3B directly and DNMT1 indirectly thereby inducing global DNA hypomethylation and tumor suppressor gene expression." (PMID 29100357, 2017). "Introduction of latent membrane protein 1 (LMP1), a viral oncoprotein from EBV, into a breast cancer cell line (MCF-7) activated DNMT1, DNMT3A, and DNMT3B, and induced methylation-silencing of tumor-suppressor gene CDH1." (PMID 26823082, 2016). "We also compared values from mammary gland and tumor in each experimental group finding, in general, a decrease of DNMT expression in tumor, mainly in DNMT3a and DNMT3b." (PMID 26401660, 2015). "Note that treatment with the MDM2 inhibitor, Nutlin-3, significantly reduces DNMT3A and DNMT3B expression and methylation of TSGs, as well as tumor growth in vivo." (PMID 25949795, 2014). "Increased expression of DNMT3A and DNMT3B as de novo DNA methyltransferase are common in many tumours which implies the that aberrant DNMT3A and DNMT3B expression are involved in carcinogenesis." (PMID 20128888, 2010). "Abnormal DNA methylation is thought to be a major early event in the development of tumours where DNA methyltransferases (DNMTs), DNMT1, DNMT3A and DNMT3B have been identified as DNA methylation functional enzymes in eukaryotic cells." (PMID 20128888, 2010). "Tumours stratified as hot, intermediate, or cold based on CD8+ T cell infiltration; identified biomarkers (HLA class I, CD8, DNMT3A) predictive of immune checkpoint inhibitor efficacy; biomarkers validated via multiplexed immunofluorescence and immunohistochemistry." (PMID 41312167, 2025). "Among the candidate biomarkers, the DNA methyltransferase DNMT3A and the guanine monophosphate synthetase (GMPS) have emerged as potential prognostic drivers, yet their roles across tumor contexts remain unclear." (PMID 41465346, 2025).
tumor (continued). "This study examines the expression levels of certain proteins (DNMT1, DNMT3A, and DNMT3B) in tumor tissue, using immunohistochemistry to assess whether these protein levels are linked to the risk of cancer recurrence or mortality." (PMID 40507223, 2025). "Genetic knockout of DNMT3A in CAR T cells mirrors this effect, bolstering anti-tumor immunity." (PMID 40927709, 2025). "Moreover, DNMT3A knockdown induces the re-expression of TP53AIP1, leading to decreased metastasis and reduced in vivo tumor growth." (PMID 41226543, 2025). "Another patient had DNMT3A p.(Arg882His) which was identified in bone marrow stromal cells and therefore unlikely to be the result of tumor contamination." (PMID 40766138, 2025). "Subsequently, low DNMT3A expression decreases methylation levels in HAVCR2 and LGALS9 promoters, promoting Tim-3 and Galectin-9 expression in HeLa and C-33A CC cells, suppressing the anti-tumor immunity mediated by innate and adaptive immune cells." (PMID 41226543, 2025). "Then, DNMT3A binds to promoters of HAVCR2 and LGALS9 genes, increasing the methylation levels in these promoters and decreasing the expression of Tim-3 and Galectin-9 in SiHa and HeLa CC cells, as well as in vivo tumor growth." (PMID 41226543, 2025). "In addition, deletion of de novo DNA methyltransferase 3 alpha (DNMT3A) provided overall resistance to CAR-T cell exhaustion, which exhibited enhanced proliferation, in vivo persistence, and tumor control in prolonged tumor exposure." (PMID 41181132, 2025). "DNMT3A and GMPS are overexpressed in tumor versus normal tissues of HCC and PDAC." (PMID 41465346, 2025). "Conversely, overexpression of HDAC7 reversed the attenuation of tumour growth and metastasis and the suppression of c-Myc and ZEB1 expression mediated by downregulation of DNMT3a, further indicating the existence of positive feedback regulation between DNMT3a and HDAC7 in LUAD." (PMID 39990668, 2025). "We also revealed that DNA methyltransferase DNMT3A could silence LDHB expression and restoring LDHB expression might suppress HCC progression through remodeling the tumor immune microenvironment." (PMID 38739169, 2024). "An increased expression level of DNMT1 has been found in tissue samples from metastatic breast tumors, whereas upregulation of DNMT3A and DNMT3B has been observed mainly at an early stage of tumorigenesis, implying a tumor stage-dependent expression pattern of these enzymes." (PMID 39334883, 2024). "DNMT3A was significantly enriched in the CCL22 and CCR4 promoter regions in tumor tissues." (PMID 39513112, 2024). "They certified that CAR-T cells lacking DNMT3A retained the ability to proliferate and generate anti-tumor responses during prolonged tumor exposure." (PMID 38622705, 2024). "In addition, we also found that, with the increase in the degree of malignancy of the tumor, the expression of TAT gradually decreased, while the expression of DNMT3A/3B gradually increased." (PMID 39334853, 2024). "In contrast to other mutations such as TET2 and DNMT3A, which can occur in both tumor and nontumor cells of AITL patients, RHOA mutations appear to be limited to tumor cells, indicating that they play an important role in AITL pathogenesis." (PMID 38023160, 2023). "The primary nodal presentation with tumor mainly involving lymph nodes, T-cell origin, lack of nasal involvement, and presence of mutations in TET2 and DNMT3A supports the diagnosis of primary nodal-EBV-TNKL." (PMID 37646869, 2023). "Interestingly, DNMT3A, a paralogue of DNMT3B, predominantly plays a tumor-suppressive role in cancers." (PMID 37072414, 2023). "In this study, the expression of DNMT1 significantly increased in After Tumor, whereas the expression of DNMT3A and DNMT3B did not change." (PMID 38136558, 2023). "These neoplasms feature a characteristic and similar, but not identical, mutational landscape with mutations in epigenetic modifiers (TET2, DNMT3A, IDH2), RHOA, and T-cell receptor signaling genes." (PMID 36793612, 2023).
tumor (continued). "Consistent with cultured cells, was the marked increase of DNMT3B expression—but not DNMT1 and DNMT3A—in GLO1-depleted MDA-MB-231 tumor xenografts when compared with control tumors." (PMID 36998085, 2023). "DNMT3A and RB1 are deleted in the MPM700 cell line and tumor." (PMID 37345150, 2023). "For example, DNMT1, DNMT3A, and DNMT3B have been shown to promote LAML, which may be due to DNMTs silencing certain tumor suppressor genes through hypermethylation of these genes, thereby promoting the progression of LAML." (PMID 37308972, 2023). "More importantly, donor T-cells lacking DNMT3A provided superior tumor control in graft-versus-leukemia models, corroborating the clinical data cited above." (PMID 37325668, 2023). "Additionally, we discovered that the levels of three DNA methyltransferases (DNMT1, DNMT3A, and DNMT3B) were significantly higher in the CBX2high tumor than the CBX2low tumor and the CEP55high tumor than the CEP55low tumor." (PMID 37980163, 2023). "In the epigenetic regulation, E7 could upregulate DNA methyltransferases DNMT1, DNMT3A, and DNMT3B to promote genomic instability 17, induce methylation of CXCL14 to promote tumor growth via angiogenesis." (PMID 34729114, 2021). "Compared with other DNA methyltransferases (such as DNMT3A), DNMT1 subtypes are not susceptible to mutation and are more suitable as targets for anti-tumor drugs." (PMID 34073721, 2021). "Similarly, the tumor migration capacity of DU145 and LNcap cells were significantly repressed by SChLAP1 knockdown, which was also completely abrogated by DNMT3a overexpression." (PMID 33589600, 2021). "Since we recently demonstrated the up-regulation of both DNMT3A and DNMT3B transcript levels in RMS tumour samples compared to normal skeletal muscle and the antitumoral effects of DNMT3B knocking down on ERMS cell lines, here, we analysed DNMT3A/3B involvement in radioresistance mechanisms." (PMID 34831178, 2021). "For example, we show that HBx- downregulated miR-101 fails to modulate DNMT3A silencing of multiple tumor suppressors in HBV-HCC while simultaneously modulating the expression of macrophages, DCs, T-cells and B-cells." (PMID 33995383, 2021). "In our study, based on the ceRNA hypothesis, tumor-promoting genes, including KCNQ1OT1, JARID2, CDK6, DNMT3A, and TET1, competitively bound the tumor suppressor gene hsa-29c-3p." (PMID 32127798, 2020). "Our current study demonstrated that the mRNA levels in cells and the protein levels in the supernatants of DNMT1, DNMT3a, DNMT3b, and HDAC1 increased with the increase of cell malignancy, which has provided a critical evidence in the search for tumor biomarkers from body fluid." (PMID 33383878, 2020). "We next measured the levels of DNMT1, DNMT3A and DNMT3B in these tumor tissues." (PMID 30948928, 2019). "The results showed that the expression of DNMT3A in tumor tissue was higher than that in the nontumor tissue (mean dCT of tumors vs. normal tissues: 1.37 vs. 0.43, p < 0.0001)." (PMID 31311130, 2019). "DNMT levels—especially those of DNMT3A and DNMT3B—are often increased in various cancer tissues and cell lines, which may partly account for the hypermethylation of CpG-rich regions in tumor suppressor gene promoters in various malignancies." (PMID 28616099, 2017). "VEGFA induced DNMT3A, but not related DNMT3B or DNMT1, and DNMT3A knockdown prevented VEGFA‐mediated miR‐128 loss and the increases in Bmi1 expression and OVCA tumor sphere formation in vitro." (PMID 28179359, 2017). "That said, the role of Dnmt3a in tumorigenesis is tissue specific, since in the lung it does not affect tumor initiation but rather tumor progression." (PMID 28425913, 2017).
tumor (continued). "Thus, HMA appears to have to inhibit DNMT3a and DNMT3b as well as DNMT1 to exert anti-tumor activities." (PMID 28052028, 2017). "DNMT3A and DNMT3B expression also correlated with tumor size." (PMID 27999365, 2016). "Both MTHFR and DNMT3A promoters showed significantly higher methylation in tumor tissue with respect to blood, and MTHFR also showed significantly higher methylation levels in tumor tissue respect to healthy adjacent thymic epithelial cells." (PMID 27999265, 2016). "Tumor DNA treatment induced increase in expression of CK20 strong positive (+++) pixels, E-cadherin weak (+) and moderate (++) positive pixels and DNMT3a weak (+) positive pixels." (PMID 26133168, 2015). "Hence, we investigated the effects of the high fat diets on DNMT function, determining mRNA levels of DNMT1, DNMT3a and DNMT3b, as well as DNMT activity in mammary gland and tumor at 246 days of age." (PMID 26401660, 2015). "Notably, DNMT1, DNMT3A, and DNMT3B are overexpressed in a coordinate manner in most tumor tissues and at a significantly higher level in cancer than in non-tumorous tissues." (PMID 25949795, 2014). "DNMT3A and DNMT3B are highly expressed in early embryonic cells, the stage in which most programed de novo methylation events occur, are downregulated after differentiation and in adult somatic tissues, and are overexpressed in tumor cells." (PMID 24822169, 2014). "Another potential tumour-suppressive miRNA in CRC development is miR-143, which might regulate DNA methylation by targeting DNA methyltransferase 3A (DNMT3A)." (PMID 24559209, 2014). "Several miR-143 targets, including DNMT3A and KRAS, and miR-145 targets including BNIP3, IRS, C-MYC, YES and STAT1, have been identified, indicating that miR-143 and 145 act as tumor suppressors to repress tumor proliferation or promote apoptosis." (PMID 22438992, 2012). "Of the CRC patients who were analysed, 80% (8 of 10) simultaneously showed a downregulation of miR-143 and an upregulation of DNMT3A in tumour tissues compared with their paired non-cancerous colonic tissues." (PMID 19638978, 2009). "Of note, the DNMT3A/TET2-associated gene module consists of genes involved in clonal hematopoiesis, so this association may not be directly related to changes in the tumor itself." (PMID 39664186, 2024). "This is consistent with DNMT3A mutations appearing rarely in tissue biopsies, and tending to appear only in high TMB tissue samples, often as passenger disruptions of the gene, but appearing frequently in liquid biopsies regardless of tumor mutational burden." (PMID 40027285, 2023). "Considering the high expression of DNMT3A, TET1, DNMT3B, TET3, UHRF2, DNMT1, UHRF1and TDG in Subtype B, changing the tumor microenvironment cell infiltration characteristics by reversing expression of these DNA methylation regulators may be more clinically practical." (PMID 35771147, 2022). "In addition, DNA methylation may play an important role in tumor progression, and PBK/TOPK expression was positively correlated with methyltransferase expression, including DNMT1, DNMT3A, and DNMT3B, in most cancers except CHOL." (PMID 34603451, 2021). "Importantly, they found that Dnmt3a inactivation by itself does not exert any obvious impact on the homeostasis of the adult tissue or tumor initiation in mice." (PMID 34968242, 2020). "Among the proteins of interest (NPM1, FLT3, DNMT3A, IDH1, IDH2, KIT, and RAS), non-mutation bearing ligands from NPM1 were the most frequent in both patient tumor samples and cell lines, including ligands close to or corresponding to where hotspot mutations occur (EAIQDLWQW and MTDQEAIQDLWQWR)." (PMID 31291378, 2019). "We found that the expression of DNMT3A correlated TNM stage but not age or tumor size." (PMID 31311130, 2019). "In contrast, DNMT3A expression was not consistent in both MYC-driven tumor types." (PMID 29100357, 2017). "Although not significant, DNMT3A presented decreased expression in the tumor samples." (PMID 28122331, 2017).